ENSG00000288684 (novel protein)
Gene: Protein-coding gene on chromosome 9 (32,455,323 to 32,552,603, reverse strand). Ensembl gene ENSG00000288684.
Genetic constraint (gnomAD): Loss-of-function variants: 65 observed, 80.76 expected, observed/expected ratio (o/e) 0.8, 90% interval 0.66 to 0.99. Missense variants: 822 observed, 969.39 expected, observed/expected ratio (o/e) 0.85, 90% interval 0.8 to 0.9. Synonymous variants: 281 observed, 323.61 expected, observed/expected ratio (o/e) 0.87, 90% interval 0.79 to 0.96.